PTPN11 (protein tyrosine phosphatase non-receptor type 11)
Diseases named in the same sentence as PTPN11 in open-access papers (continued):
Sharing a sentence is not in itself a finding about the gene and the disease.
cancer (continued). "Some somatic PTPN11 cancer mutations are similarly clustered in testis." (PMID 36349709, 2022). "Somatic PTPN11 variants are associated with cancer, and frequently found inJMML." (PMID 35778969, 2022). "The general distribution of PTPN11 germline missense mutations differs from the distribution of PTPN11 cancer-associated somatic mutations, with a mutation hotspot at the beginning of the PTP domain in the germline set of mutations that is not that clearly manifested in the set of somatic mutations." (PMID 36755664, 2022). "Somatic mutations in PTPN11 have been found to cause cancer." (PMID 36407105, 2022). "Some examples are PTPN11 that is known to activate a transcriptional program associated with cancer stem cells or the EMT-related genes SOX4 or VIM that might be responsible for the high invasive capacity of the tumors and their early metastasis formation." (PMID 33706810, 2021). "Furthermore, mutation or loss of PTPN11, a tyrosine phosphatase, have also been detected in number of cancer, including breast cancer, gastric cancer, acute myeloid leukemia, lung cancer, colorectal cancer." (PMID 28750679, 2017). "Gain-of-function PTPN11 mutations have been found in various types of human cancer." (PMID 25198338, 2014). "Furthermore, PTPN11 mutations are known to confer resistance to chemotherapy and targeted therapies in other cancers, which could account for the failure of high-dose ARA-C in this case." (PMID 40141849, 2025). "Notably, our results suggest that PTPN11 loss-of-function mutations may be a cancer-agnostic predictive marker of immunotherapy benefit." (PMID 36463294, 2022). "Mutations in PTPN11 are implicated in various developmental disorders and hematological diseases, while wild-type (WT) SHP2 is a pivotal target in cancer therapy." (PMID 41658103, 2026). "By stabilizing an open, active SHP2 conformation, pY62 phenocopies oncogenic PTPN11 mutations and sustains MAPK signaling across cancer types." (PMID 40667115, 2025). "Bulk and single-cell transcriptomic data from public databases were utilized to perform pan-cancer analysis for mining the oncogenic potential of PTPN11, accompanied by functional enrichment, immune infiltration, and drug molecular docking analyses." (PMID 41367010, 2025). "Specifically, PTPN6 and PTPN11 are involved in the phosphoinositide 3 kinase/AKT/mammalian target of rapamycin (PI3K/AKT/mTOR) signaling pathway, which has been implicated in cancer progression and metastasis." (PMID 40806280, 2025). "In a recent study, we showed that variant profiles in the PTPN11 and KRAS genes of HHS-affected dogs is similar to that observed in HS samples, suggesting the dysregulation of common signaling pathways in both cancer types." (PMID 40149290, 2025). "This review aims to summarize current knowledge on SHP2/PTPN11 biology, its role in immune regulation, cancer progression, and vascular homeostasis, and to discuss emerging therapeutic strategies targeting this pathway." (PMID 41462587, 2025). "The most common cancer observed across all (except PTPN11 heterozygotes) of the gene-syndrome groupings was malignancy of the skin." (PMID 39802765, 2024). "As of December 2023, at least ten PTPN11 inhibitors have reached Phase I/II clinical trials for the treatment of solid tumours either as monotherapies or in combination with other anti-cancer drugs, including TKIs and immune checkpoint inhibitors." (PMID 38334623, 2024). "Subsequently, the anti-cancer effects of allosteric PTPN11 inhibitors have been widely assessed in pre-clinical models and are under evaluation in early-stage clinical trials for the treatment of cancer." (PMID 38334623, 2024). "Of note, allosteric PTPN11 inhibitors have shown high specificity over the related PTPN6 whilst retaining anti-cancer effects in pre-clinical studies and early-stage clinical trials." (PMID 38334623, 2024).
cancer (continued). "Encouragingly, the results from a Phase 1 trial indicated that the use of the allosteric PTPN11 inhibitor PF-07284892 was able to overcome resistance to diverse TKIs in a range of cancer types." (PMID 38334623, 2024). "There was a decrease in expression of a number of anti-cancer genes (e.g., Casp3, Mgmt, Parp1, Ptpn11) as well as an increase in several cancer-promoting genes (e.g., Ly6a, Lgr5, Vnn1)." (PMID 38151490, 2023). "This led to the description of PTPN11 as an atypical phosphatase with oncogenic properties, which makes PTPN11 a suitable target for cancer therapy." (PMID 37384296, 2023). "Our pan-cancer analysis of PTPN11 through the TCGA database also confirmed abnormal expression of PTPN11 in multiple tumors and a significant correlation with patient prognosis." (PMID 37892971, 2023). "For example, there was a decrease in expression of a number of anti-cancer genes including pro-apoptotic gene Casp3, DNA repair genes Mgmt and Parp1 and tyrosine phosphatase Ptpn11." (PMID 37886485, 2023). "Allosteric inhibition of PTPN11 via SHP099 suppressed the RTK-driven human cancer cells by inhibiting the RAS-ERK signaling pathway." (PMID 37892971, 2023). "PTPN11 has always been a focus of attention in the field of human diseases, especially cancer, and can bind to multiple immune inhibitory receptors and inhibit the activation of immune cells." (PMID 37884566, 2023). "Autosomal dominant activating mutations in PTPN11 fuel excess RAS/ERK1/2 signaling that drives certain human RASopathies and cancers." (PMID 37836790, 2023). "In the head and neck squamous cell carcinoma, PTPN11 promotes invadopodia formation through suppression of Rho signaling, leading to cancer metastasis." (PMID 35957898, 2022). "SHP2 tyrosine phosphatase (SH2 domain containing phosphatase 2, also known as PTPN11) has recently emerged as a key player in cell proliferation and immunity, providing an attractive therapeutic target for cancer." (PMID 36114179, 2022). "Then “Pathologic Stage Plot” module in GEPIA2 was utilized in order to examine how PTPN11 expression correlated with the pathologic phase of cancers." (PMID 35802774, 2022). "Although PTPN11 has been studied separately in several tumors, pan-cancer evidence has yet to be established to elucidate the potential impact of PTPN11 in divergent malignancies in the previous researches." (PMID 35802774, 2022). "Using the cBioPortal tool, we evaluated the genetic modification state of PTPN11 in distinct cancers from TCGA dataset." (PMID 35802774, 2022). "As an example, PTPN11 (also known as SHP2) is a protein tyrosine phosphatase working downstream of RTKs and that has been associated with several cancer types." (PMID 35882839, 2022). "There was an inconsistent expression of PTPN11 in different tumors, and the alteration of PTPN11 expression predicted the survival outcomes of cancer patients." (PMID 35802774, 2022). "Recently, an allosteric inhibitor of PTPN11 has been reported and used in clinical trials for genetic disorders and cancer treatment." (PMID 35563411, 2022). "PTPN11 was a cancer-related gene that induced macrophages to differentiate into type M1 via activation of RELA signalling, which promoted inflammatory response as well as induced carcinogenesis." (PMID 36382627, 2022). "We examined the changes of PTPN11 phosphorylation levels among cancer tissues and corresponding healthy tissues using the CPTAC database." (PMID 35802774, 2022). "Our results suggested that nearly all the immune-related genes were significantly related to PTPN11 and most were negatively related to PTPN11 across most cancers." (PMID 35802774, 2022). "The discrepancies of PTPN expression indicated that PTPN11 played different roles in many aspects of cancer biology, including the processes of cell division, repair of DNA, metastasis, and angiogenesis." (PMID 35802774, 2022).
cancer (continued). "In accordance with prior research, our pan-cancer analysis of PTPN11 revealed differential expression in diverse tumors." (PMID 35802774, 2022). "PTPN11, which is considered an oncogenic factor and a key target for cancer immunotherapy according to several studies, is mediated by several miRNAs." (PMID 35957898, 2022). "Although PTPN11 inhibitors have shown promising effects in some cancers driven by aberrant RTK signalling or activated PTPN11, we did not observe a reduction of RMS559 viability when treating the cells with the SHP099 inhibitor." (PMID 36097178, 2022). "Secondary outcome measurement is enrichment of RAS regulatory gene (NF1, PTPN11, and CBL) in BRAF variant cancers." (PMID 33507258, 2021). "PTPN11 acts as an oncogenic phosphatase in several cancer types by dephosphorylation of a wide variety of effector and regulatory signaling proteins, mainly acting downstream of RTKs to promote activation of the RAS/MAPK pathway." (PMID 34957126, 2021). "Accordingly, pharmacological inhibitors of PTPN11 catalysis have emerged as potential anti-cancer drugs, making the elucidation of the cancer type-specific PTPN11 substrates an important demand." (PMID 34957126, 2021). "Germline and somatic mutations in PTPN11 are associated with different rare diseases and hematologic malignancies,and recent studies have individuated SHP2 as a central node in oncogenesisand cancer drug resistance." (PMID 32395997, 2020). "Development of the tyrosine phosphatase SHP2 (PTPN11) inhibitors has been the focus of considerable research efforts in light of their diverse role in cancer and RASopathies disorders." (PMID 32676024, 2020). "It was reported that PTPN11 play an important role in promoting progression and metastasis of cancer 38-41." (PMID 32194783, 2020). "The Src homology-2 (SH2) domain-containing protein tyrosine phosphatase 2 (SHP2, encoded by PTPN11) has been one of the hottest topics in the world and has attracted much attention to study the possibility in cancer." (PMID 33330386, 2020). "SHP2 cancer mutants (SHP2G60V, SHP2D61V, SHP2E76K, SHP2F285S, and SHP2S502P) introduced into PTPN11-null U2OS cells were expressed in amounts comparable to the reintroduced SHP2WT in the SHP2-null cells." (PMID 30375388, 2018). "Increased expression of PTPN11 is currently postulated to be a key element in intrinsic and acquired resistance to other targeted cancer drugs." (PMID 30201928, 2018). "Of the four top hits, KDR and PTPN11 were included in screening 1,001 cancer cell lines in the Genomics in Drug Sensitivity in Cancer database." (PMID 29383146, 2017). "Among these, five novel mutations in cancer-related genes (KDR, STK11, MLH1, KRAS, and PTPN11) were detected in ES, and these mutations were confirmed with traditional Sanger sequencing." (PMID 27077911, 2016). "Tyrosine phosphorylated CagA by SRC family kinases interacts with SHP2 tyrosine phosphatase (encoded by the PTPN11 oncogene), CRK, CRKL and CSK and induces cell scattering, dissociation and mortality connected to cancer development." (PMID 22383989, 2012). "Knockdown of PTPN11 significantly decreased cancer cell growth compared with si-control transfectants." (PMID 20700123, 2010). "SHP2 is also involved in acquired resistance to anticancer drugs, and it was suggested that the activated gene PTPN11 could be assumed as a biomarker for acquired chemoresistance in cancer." (PMID 41302504, 2025). "Complementation with empty vector control was not tolerated by cells, consistent with PTPN11/SHP2 loss being synthetic lethal in RTK-driven cancer cells." (PMID 40667115, 2025).
cancer (continued). "Therefore, there is compelling evidence to support the identification of SHP2 as a bona fide oncoprotein; accordingly, SHP2 inhibition or PTPN11 deletion were shown to prevent the progression of cancers driven by PTKs." (PMID 41302504, 2025). "Phosphorylation of PTPN11 at Y62 impact the activation of RAS/MAPK and PI3K/AKT signalling pathways for cell survival and proliferation, and has been implicated to drug resistance in cancer." (PMID 39695132, 2024). "Conversely, restoration of PTPN11 enhances the sensitivity of cancer cells to the PI3K inhibitor." (PMID 39068158, 2024). "As a result of genomic profiling following the cancer diagnosis, two of four PTPN11-positive individuals within our NCH pediatric/adolescent and young adult (AYA) cancer cohort (individuals 2 and 3) received an NS diagnosis following their cancer diagnosis as a result of paired exome sequencing." (PMID 39309743, 2024). "Future work could explore in depth the functional role of the PTPN11 phosphorylated residues (Y62, Y542 and Y580) in signalling activation, drug resistance and cancer immunity in the EML4-ALK + NSCLC." (PMID 39695132, 2024). "The protein tyrosine phosphatase SHP2, encoded by the PTPN11 gene, participates in several cellular functions, including gene transcription, cytokine signaling, cell differentiation, and the proliferation and migration of cancer cells." (PMID 38747738, 2024). "This key function of SHP2 is also reflected by its frequent dysregulation in cancer, either resulting from overexpression of its activators such as docking/adapter proteins of the GAB and FRS families or from the amplification or gain-of-function mutations of PTPN11 itself." (PMID 39120280, 2024). "Notably, in the PD-1/PD-L1 cancer immunotherapy pathway, CD274, the gene that transcribes PD-L1, PDCD1LG2, the gene that transcribes PD-L2, and PTPN11, the gene that encodes SHP2 are all predicted to be activated by IFNγ in astrocytes." (PMID 37828609, 2023). "However, comprehensive analysis of PTPNs is still missing at the pan-cancer level, especially in AML, and most studies focus on proving the clinical value of PTPN1 expression and PTPN11 mutation in AML14,15." (PMID 37884566, 2023). "Furthermore, the PTPN11 gene has been identified as a drug target for the intrinsic and acquired drug resistance of cancer drugs, which has important implications for clinical treatment." (PMID 38025540, 2023). "SHP2, a non-receptor protein tyrosine phosphatase encoded by the PTPN11 gene, is widely expressed in adult tissues and associated with numerous cancers." (PMID 37669923, 2023). "Moreover, the CPTAC database was utilized to evaluate the impact of PTPN11 phosphorylation on cancers." (PMID 35802774, 2022). "Studies reported the SH2 domains of PTPN11 could bind to programmed cell death 1 (PD-1), an immune checkpoint target for cancer immunotherapy, to suppress T cell function and stimulate the immune escape of cancer cells." (PMID 35802774, 2022). "In addition, the heat map confirmed the remarkably positive relation among PTPN11 expression and above five genes in most cancers." (PMID 35802774, 2022). "Six of the PTPN11 exon 3 de novo variants associated with somatic mutation‐induced sporadic cancers (but not NS) also formed testis clusters." (PMID 36349709, 2022). "The results were consistent with previous work, which indicated that PTPN11 could either operate as an oncogenic element or a cancer inhibitor in certain illnesses." (PMID 35802774, 2022). "Furthermore, we detected the PTPN11 protein expression levels in different cancers by the HPA cohort." (PMID 35802774, 2022). "Importantly, PTPN11(Shp2) inhibition has recently emerged as a therapeutic target in multiple cancer models." (PMID 35574218, 2022). "PTPN11 is located within a linkage disequilibrium block associated with RA and encodes a cytoplasmic tyrosine phosphatase SHP-2, a known proto-oncogene and cancer target." (PMID 35265082, 2022).
cancer (continued). "Accumulating evidence has provided promising results regarding inhibitors of the nonreceptor protein tyrosine phosphatase SHP2, encoded by PTPN11, in cancer." (PMID 34885068, 2021). "The mutation of the PTPN11 gene is not the only causative link to NS and LS but is also one of the most somatic mutated genes (SMGs) in cancer pathogenesis." (PMID 32676024, 2020). "Indeed, male germ-line-selective advantage has previously been described for mutations in other genes involved in cancer (e.g. FGFR2, FGFR3, RET, PTPN11) that cause congenital disorders with paternal age effect." (PMID 28733602, 2017). "However, increasing evidence suggests that certain PTPs can also promote cancer development (i.e., act as oncogenes), such as the PTP Shp2 (src homology 2 domain-containing tyrosine phosphatase 2), which is encoded by PTPN11." (PMID 29207630, 2017). "Interestingly, PTPN11 and a receptor for IL8, CXCR1, have also been implicated in cancer stem cell self-renewal in the breast." (PMID 23113900, 2012). "Furthermore, cancers driven by mutant KRAS are dependent on PTPN11 expression." (PMID 38334623, 2024). "Furthermore, we observed PTPN11 was negatively related to the immunostimulants, immunosuppressants, MHCs, TILs, chemokines, and receptors in most cancers, which might further confirm the complexity of the TME." (PMID 35802774, 2022). "In addition, we observed PTPN11 expression was highly correlated with MMR gene expression, which suggested that patients with related cancers may benefit from taking mutant PTPN11 into account when assessing development and prognosis." (PMID 35802774, 2022). "Taken together, PTPN11 may become a new biomarker and target for cancer therapy." (PMID 35802774, 2022). "Besides RAS-activating mutations that confer independence from physiological regulators, human cancers harbor mutations in other RAS network genes such as NF1 (encoding neurofibromin, a RAS GAP), BRAF, or PTPN11 (encoding the SHP2 tyrosine phosphatase involved in RAS activation)." (PMID 35354920, 2022). "Thus, both the catalytic activity and the expression levels of PTPN11 are relevant in human cancer." (PMID 34957126, 2021). "Moreover, ChIP-chip assays yielded a total of 48 genes enriched in at least three of the seven primary samples including genes associated with cell cycle such as ARGHEF2, CCNA2, CDKN2D, GAK2, ORCL6, PCPNP, and TACC1 and genes associated with cancer such as AR, AXIN2, IKBKG, ETS1, PTPN11, and WNT2B." (PMID 23300998, 2013). "Background/Objectives: SHP2 (PTPN11) is a key regulator of RAS/MAPK signaling and a well-validated target in cancer and developmental disorders." (PMID 42198380, 2026). "Pan-cancer analysis revealed that PTPN11 expression levels (high vs low) were significantly correlated with survival differences in PTC and other cancers (P < .05)." (PMID 41367010, 2025). "The PTPN11 (SHP2-E76K) hotspot predicts RAS/MAPK activation and prevalent in various cancer types, leading to the active investigation of SHP2 inhibitors and downstream MEK/ERK blockade." (PMID 41378284, 2025). "Several compounds that target phosphatases including PTPN11/SHP-2 and PTPN1/PTPN2 have shown remarkable efficacy in preclinical studies and are in early phase clinical trials for the treatment of cancer." (PMID 39039893, 2024). "Among newly identified genes, eleven other cancer targets were detected: MPL; ERBB4; VHL; FGFR3; KIT; KDR; PTEN; KRAS; PTPN11; ERBB2; and SMARCB1." (PMID 35621644, 2022). "IL22RA1 was positively correlated with STAT1, STAT3, JAK1, PTPN11, IFNA13, IL24, but negatively correlated with IL10 in specific cancers." (PMID 35874683, 2022).